FHOD3 (formin homology 2 domain containing 3)
Description:
Actin-organizing protein that may cause stress fiber formation together with cell elongation (By similarity). Isoform 4 may play a role in actin filament polymerization in cardiomyocytes.
Synonyms: FHOS2; KIAA1695; FLJ22297; FLJ22717; CMH28; Formactin2
Tractability: No criterion of Open Targets' tractability assessment is met for any kind of drug.
Gene: Protein-coding gene on chromosome 18 (36,297,676 to 36,780,220, forward strand). Ensembl gene ENSG00000134775.
Subcellular location: Cytoplasm, cytoskeleton; Cytoplasm, myofibril, sarcomere, Z line (Isoform 4)
Gene Ontology:
Molecular function: protein binding; actin filament binding
Biological process: actin filament organization; cardiac myofibril assembly; positive regulation of stress fiber assembly; sarcomere organization
Cellular component: cytoplasm; cytoskeleton; Z disc
Genetic constraint (gnomAD): Loss-of-function variants: 75 observed, 152.73 expected, observed/expected ratio (o/e) 0.49, 90% interval 0.41 to 0.6. The upper end of that interval is the gene's LOEUF score, 0.6, which puts it in group 2 of 6, group 1 being the genes least tolerant of losing a copy. Missense variants: 1,863 observed, 1,984.9 expected, observed/expected ratio (o/e) 0.94, 90% interval 0.9 to 0.98. Synonymous variants: 805 observed, 801.9 expected, observed/expected ratio (o/e) 1, 90% interval 0.95 to 1.06.
Gene-disease validity (ClinGen):
ClinGen rates the evidence that FHOD3 causes each of these diseases.
hypertrophic cardiomyopathy (autosomal dominant): Definitive. A condition in which the myocardium is hypertrophied without an obvious cause.
Homologues: Orthologues: chimpanzee FHOD3 (99% identical), macaque FHOD3 (98% identical), dog FHOD3 (90% identical), pig FHOD3 (88% identical), rabbit FHOD3 (87% identical), mouse Fhod3 (86% identical), rat Fhod3 (86% identical), guinea pig FHOD3 (80% identical), tropical clawed frog fhod1 (43% identical), Caenorhabditis elegans daam-1 (11% identical). Paralogues in human: FHOD1 (36% identical), FMNL2 (13% identical), FMNL1 (13% identical), FMNL3 (12% identical), DIAPH1 (12% identical), DIAPH3 (12% identical), DAAM1 (12% identical), DAAM2 (12% identical), INF2 (12% identical), DIAPH2 (11% identical), GRID2IP (11% identical), FMN2 (10% identical), and 6 more.
Diseases named in the same sentence as FHOD3 in open-access papers:
FHOD3 is named in the same sentence as 32 diseases in open-access papers, as found by Europe PMC text mining. Sharing a sentence is not in itself a finding about the gene and the disease. The quoted sentences say what the papers report.
cardiomyopathy (11 papers, 2017 to 2025). A disease of the heart muscle or myocardium proper. "We describe the recent understanding of the functional impact of titin variants and highlight FHOD3 as a novel cardiomyopathy-associated gene." (PMID 38771459, 2024). "Fhod3, which is abundantly expressed in the heart, localizes to the center of sarcomeres and contributes to the regulation of the cardiac function, as evidenced by the fact that mutations in Fhod3 cause cardiomyopathy." (PMID 39384365, 2024). "With the inclusion of the FHOD3 in cardiomyopathy gene panels, the prevalence of FHOD3-associated HCM could be significantly higher than currently estimated, particularly among patients with HCM with Balkan ancestry." (PMID 38051749, 2023). "Three of the DCM-associated genes, FLNC, TTN (through its kinase activity) and cardiac specific FHOD3 encode maintenance partners of sarcomere and sarcomere-related structures, including Z-disk or F-actin myofibrils, which are disorganized or degraded in experimental models of cardiomyopathy." (PMID 28296976, 2017). "We identified common variants within genes implicated in cardiomyopathies (e.g. BAG3, FHOD3, PLN), suggesting sarcomere homeostasis during mechanical stress may affect diastolic function in both health and disease." (PMID 35479509, 2022).
hypertrophic cardiomyopathy (9 papers, 2021 to 2026). "Genetic variants of FHOD3 have been linked to hypertrophic cardiomyopathy (HCM), dilated cardiomyopathy (DCM), and an increased risk of cardiovascular mortality." (PMID 41462520, 2025). "FHOD3 is essential for myofibrillogenesis at an early stage of heart development and has been identified as a causal gene for hypertrophic cardiomyopathy with related heart rate abnormalities in humans." (PMID 38969939, 2024). "Mutations in FHOD3 are strongly linked to hypertrophic cardiomyopathy and are also associated with dilated cardiomyopathy." (PMID 37215084, 2023). "Human genetic studies have identified multiple FHOD3 variants linked to dilated and hypertrophic cardiomyopathies, with many mutations mapping to “hot spots” in FHOD3 domains." (PMID 37215084, 2023). "Finally, a human genome analysis revealed that human mutations in Fhod3 indeed cause hypertrophic cardiomyopathy, indicating the critical role of Fhod3 in cardiac muscle." (PMID 39384365, 2024). "Moreover, we identified one pathogenic variant in the FHOD3 gene that was previously associated only with hypertrophic cardiomyopathy (HCM)." (PMID 37342443, 2023). "MyBCP acts as a sarcomeric tether for FHOD3, as mice null for MyBCP lack FHOD3 in their cardiac sarcomeres and develop hypertrophic cardiomyopathy." (PMID 37215084, 2023). "The FHOD3 and DTNA genes are considered candidate genes associated with hypertrophic cardiomyopathy, a heart disease that affects all age groups, being the most common cause of heart failure and sudden death." (PMID 34249494, 2021). "Genes associated with Mendelian forms of hypertrophic cardiomyopathy (HCM) (MYBPC3, ALPK3 and FHOD3) were also identified at genomic risk loci for DCM, a finding consistent with evidence that these disorders represent opposing extremes of a continuum of ventricular structure and systolic function." (PMID 39572783, 2024).
dilated cardiomyopathy (5 papers, 2021 to 2025). Cardiomyopathy which is characterized by dilation and contractile dysfunction of the left and right ventricles. "The variants in VCL, SLC22A5, and FHOD3 have been shown earlier to be associated with HCM or dilated cardiomyopathies (DCM)." (PMID 37342443, 2023). "The variant FHOD3 associated with dilated cardiomyopathy was in the FH2 domain and appeared to disrupt FHOD3’s ability to stimulate SRF-dependent transcription, an activity dependent on formin stimulation of actin polymerization." (PMID 37215084, 2023). "Two intronic variants of FHOD3 have also been related to hypertrophic cardiomyopathy development and a conservative substitution (p.Val1151Ile) with a reduced risk of dilated cardiomyopathy." (PMID 34685534, 2021). "Finally, we identified a rare protein-altering variant (rs151313792) in FHOD3, a gene that regulates actin assembly in cardiac sarcomeres and has been associated with dilated cardiomyopathy and left ventricular ejection fraction." (PMID 33961016, 2021). "Transgenic mice expressing FHOD3 defective in actin binding have a similar phenotype to that of dilated cardiomyopathy patients." (PMID 34685534, 2021). "FHOD3 mutations have been associated with hypertrophic (CMH28, MIM: 619402) and dilated cardiomyopathies, which are conditions in which the walls of the heart becomes thicker and stiff, and where the heart is enlarged, respectively." (PMID 34685534, 2021). "However, FHOD3 expression is unchanged in hearts of mice expressing lamin A H222P, a model of dilated cardiomyopathy, so upregulation of FHODs by LINC complex disruption may not be typical of all cell types." (PMID 37215084, 2023).
heart failure (5 papers, 2019 to 2025). Inability of the heart to pump blood at an adequate rate to meet tissue metabolic requirements. "Our top candidates included previously known modifier genes (FHOD3), a gene known to cause DCM and HCM when mutated (TTN) and genes associated with related cardiovascular phenotypes such as heart failure (HNRNPC) and arrhythmia (CACNA1C, RYR2)." (PMID 40791945, 2025). "Whilst QKI-5 overexpression significantly attenuated heart failure through regulating the expression of specific circular RNAs derived from the from the Titin (Ttn ), Formin homology 2 domain containing 3 (Fhod3 ) and Striatin/calmodulin-binding protein 3 (Strn3 ) genes." (PMID 36010571, 2022). "In doxorubicin-induced heart failure, the RBP Qki5 interacts with circRNAs Ttn, Fhod3, and Strn3 to improve cardiac function." (PMID 30736838, 2019).
cardiac hypertrophy (4 papers, 2018 to 2022). "Increased ROCK2 was associated with the pathogenesis of Ang-II-induced cardiac hypertrophy via regulating FHOD3 phosphorylation." (PMID 32685439, 2020). "The expression and phosphorylation of FHOD3 is increased in cardiomyocytes purified from Angiotensin II-induced rat cardiac hypertrophy models, while the activation of FHOD3 inhibited by Y27632 attenuates Angiotensin II-induced cardiomyocyte hypertrophy." (PMID 36428995, 2022). "In cultured rat cardiomyocytes, angiotensin II signaling regulates FHOD3 activation through phosphorylation of its C-terminal region by ROCK kinase, raising the possibility that pathogenic FHOD3 causes heart hypertrophy by this mechanism." (PMID 34685534, 2021). "ROCK2 also plays an important role in Ang II-induced hypertension and cardiac hypertrophy, through processes that involve formin Homology 2 domain containing 3 (FHOD3), crucial in regulating myofibrillogenesis in cardiomyocytes." (PMID 29394331, 2018).
diabetes (2 papers, 2019 to 2025). "AIM2 and FHOD3 could serve as novel diagnostic and therapeutic targets for older adults with diabetes." (PMID 41462520, 2025). "Consistent with previous data, our data revealed a lower abundance of FHOD3 in the SAT of older adults with diabetes." (PMID 41462520, 2025). "According to data from the GEO datasets, AIM2 showed relatively high expression levels in the adipose tissue of older adults with diabetes, while exhibiting lower FHOD3 expression levels than those of the older healthy group." (PMID 41462520, 2025).
hearing loss (2 papers, 2021 to 2024). "Further investigations into the molecular mechanisms underlying Fhod3-mediated actin dynamics and its interaction with other proteins involved in hearing loss will deepen our understanding of the disease and pave the way for targeted therapeutic strategies." (PMID 38498576, 2024). "Through quantitative PCR (qPCR) analysis, we found significantly higher levels of Fhod3 mRNA in D2 cochleae, a model of early-onset progressive hearing loss." (PMID 38498576, 2024). "In this study, we focused on investigating the potential involvement of Fhod3 in high-frequency and progressive hearing loss, despite the presence of several other candidate genes within the 1Mb interval of the haplotype block." (PMID 38498576, 2024). "Other formin proteins have been associated with hereditary hearing loss, suggesting that altered expression of Fhod3 in our mutant mouse models may contribute to the underlying molecular mechanisms of hearing loss." (PMID 38498576, 2024). "Further investigation of Fhod3 related hearing impairment mechanisms may lend new insight towards the myriad mechanisms underlying ARHL, which in turn could facilitate the development of therapeutic strategies for ARHL." (PMID 38498576, 2024).
age-related hearing loss (1 paper, 2024). "Here we provide compelling evidence for the crucial role of Fhod3, identified through a meta-analysis of GWAS for age-related hearing loss (ARHL), in maintaining proper hair cell structure and auditory function." (PMID 38498576, 2024).
colorectal cancer (1 paper, 2010). A primary or metastatic malignant neoplasm that affects the colon or rectum. "In addition, FHOD3 and MAP2K4 were previously defined as candidate cancer genes (CAN gene) by integrated analysis of homozygous deletions and sequence alterations in breast and colorectal cancers." (PMID 21108794, 2010).
familial cardiomyopathy (1 paper, 2017). An instance of cardiomyopathy that is caused by an inherited modification of the individual's genome. "All candidate genes but one (SLC39A8) exhibit preferential expression in striated muscle tissues and mutations in TTN, BAG3, FLNC and FHOD3 are known to cause familial cardiomyopathy." (PMID 28296976, 2017).
idiopathic dilated cardiomyopathy (1 paper, 2012). Decreased function of the heart associated with cardiac enlargement and congestive heart failure, of unknown cause. "Furthermore, we also tested Fhod3 localization in human hearts with idiopathic dilated cardiomyopathy or idiopathic hypertrophic cardiomyopathy." (PMID 22509354, 2012).
left ventricular noncompaction (1 paper, 2025). Left ventricular noncompaction (LVNC) is a rare cardiomyopathy characterized anatomically by prominent left ventricular trabeculae and deep intratrabecular recesses causing progressive systolic and diastolic dysfunction, conduction abnormalities, and occasionally thromboembolic events. "Mutations in the FHOD3 gene are deemed causative in at least 1–2% of patients with hypertrophic cardiomyopathy (HCM), in addition to cases of left ventricular noncompaction (LVNC), dilated cardiomyopathy (DCM), and progressive high-frequency hearing loss." (PMID 39464085, 2025).
medulloblastoma (1 paper, 2021). A malignant, invasive embryonal neoplasm arising from the cerebellum. "Similarly, FHOD3 promotes the occurrence of medulloblastoma by regulating RhoA/ROCK1/LIMK1 signaling." (PMID 34486491, 2021).
thyroid cancer (1 paper, 2021). "For instance, FHOD3 mRNA overexpression in thyroid cancer is associated with hypomethylation of the FHOD3 promoter and with gene copy number variation." (PMID 34685534, 2021).
cancer (6 papers, 2010 to 2025). A tumor composed of atypical neoplastic, often pleomorphic cells that invade other tissues. "FHOD3 produces three isoforms via alternative splicing and plays a role in actin regulation, contributing to organogenesis, tissue homeostasis, and cancer-cell invasion." (PMID 41462520, 2025). "Further research found that ROCK-dependent phosphorylation and FH1/FH2 domain-containing protein 3 (FHOD3)–dependent activation were key mechanisms for cancer cells to mediate invasive migration via the RCP-α5β1 integrin pathway." (PMID 33041823, 2020).
cardiac disease (4 papers, 2018 to 2023). "The association of FHOD3 with cardiac disease is consistent with mouse knockout studies showing FHOD3 plays a role in normal cardiac development and homeostasis." (PMID 37215084, 2023).
infection (1 paper, 2022). The state of being infected such as from the introduction of a foreign agent such as serum, vaccine, antigenic substance or organism. "The differentially expressed proteins post-infection include Akap1, Prkaca, Prkab2, Acaca, Acacb, Aka1, Abcf1, Synj1, Braf, Vcl, and Fhod3, which involve insulin receptor signal, glucagon signal pathway, AMPK signal pathway, and Hippo signal pathway." (PMID 35313969, 2022).
FHOD3 also shares sentences with these, for which no sentence is quoted: tumor (2 papers); aortic stenosis (1); Arrhythmia (1); asthma (1); breast carcinoma (1); COVID-19 (1); Hearing impairment (1); Hypertension (1); Intellectual disability (1); intrinsic cardiomyopathy (1); peripheral neuropathy (1); primary ovarian insufficiency (1); renal disease (1); rheumatoid arthritis (1); Thrombocytopenia (1).